COL3A1 (collagen type III alpha 1 chain)
Diseases named in the same sentence as COL3A1 in open-access papers (continued):
Sharing a sentence is not in itself a finding about the gene and the disease.
metastatic melanoma (1 paper, 2025). A melanoma that has spread from its primary site to another anatomic site. "COL3A1, COL5A2 and VEGFA showed dataset-specific correlations; COL3A1 had strong associations with M1 macrophages, while VEGFA was positively correlated with CD4 T cells in metastatic melanomas." (PMID 40943183, 2025).
metastatic tumors (1 paper, 2025). "COL3A1, COL5A2, VCAN, CCND2, JAG2, and VTN showed consistent positive correlations with all three scores in both primary and metastatic tumors, suggesting their involvement in enhancing stromal support and recruiting immune cells." (PMID 40943183, 2025).
mucinous ovarian cancer (1 paper, 2018). An invasive malignant neoplasm that arises from the ovary and is characterized by the presence of malignant epithelial cells that contain intracytoplasmic mucin and may resemble the epithelial cells of the endocervix or gastrointestinal tract. "The immunohistochemical analysis of LOX, COL1A2, COL3A1, COL21A1, and ALDH1A1 was performed for few cases of endometrioid, serous, and mucinous ovarian cancer in order to verify the localization of analyzed proteins in the real cancer tissue." (PMID 30583585, 2018).
muscular dystrophy (1 paper, 2019). Muscular dystrophy (MD) refers to a group of more than 30 genetic diseases characterized by progressive weakness and degeneration of the skeletal muscles that control movement. "Another pathway placed the COL3A1 gene, which was shown to be upregulated in muscular dystrophy, downstream of miR-29, whose loss was indeed connected to dystrophic muscle pathogenesis." (PMID 31114913, 2019).
myelofibrosis (1 paper, 2022). A partial or complete replacement of the bone marrow stroma by fibrous tissue. "Interestingly, a similar degree of myelofibrosis, as measured by reticulin staining and Col3a1 mRNA expression, was observed in control and Dmp1-Cre Tgfbr2fl/fl recipients." (PMID 35439167, 2022). "However, treatment with CC-930 resulted in the nearly complete abrogation of myelofibrosis, as assessed by reticulin fibrosis, collagen I deposition, and Col3a1 mRNA expression." (PMID 35439167, 2022). "Surprisingly, the degree of myelofibrosis was similar in control and Osx-Cre Smad4fl/fl recipients, as measured by reticulin staining, collagen I and III immunofluorescence, and Col3a1 mRNA expression." (PMID 35439167, 2022).
myoma (1 paper, 2025). "They found that miR-29 levels were reduced in myoma tissue, which correlated inversely with the expression of genes such as COL3A1, responsible for collagen production, a key component of the ECM." (PMID 40672945, 2025).
non-alcoholic fatty liver diseases (1 paper, 2020). "Intriguingly, our previous studies showed that EGCG treatment shared four common collagen-related genes Col1a1, Col1a2, Col3a1 and Col6a3 with atorvastatin treatment in non-alcoholic fatty liver diseases." (PMID 32290071, 2020).
orchitis (1 paper, 2021). Inflammation of one or both testes due to viral or bacterial infections. "In all the collagen members detected to be expressed in Lc, the expression profile shifted greatly during EAO, and Col3a1, Col4a1, and Col1a2 became the main collagens expressed during orchitis." (PMID 35111154, 2021).
organizing pneumonia (1 paper, 2016). "Gene expression profiling of human and murine organizing pneumonia lesions showed in part comparable expression levels of pivotal genes, notably of TGFB1/Tgfb1, TIMP1/Timp1, TIMP2/Timp2, COL3A1/Col3a1, CXCL12/Cxcl12, MMP2/Mmp2 and IL6/Il6." (PMID 27282780, 2016).
pancreatitis (1 paper, 2017). Inflammation of the pancreas. "(D) qRT-PCR for transgenic Kras*, Fn1, Col1a1, Col3a1, Shh, Hbegf, Ereg, Areg, Tgfα and Egf in littermate control and iKras*;CD11b-DTR pancreata 3 weeks post pancreatitis and in iKras*;CD11b-DTR pancreata following DT treatment for 3 days and 1 week." (PMID 28980940, 2017).
papilloma (1 paper, 2022). A benign epithelial neoplasm that projects above the surrounding epithelial surface and consists of villous or arborescent outgrowths of fibrovascular stroma. "Hence, we analyzed the expression of selected ECM components in skin tumors by qRT-PCR and found that the mRNA levels of α1 chains of collagen I (Col1a1) and III (Col3a1) and Tnc were significantly higher in Itga11+/+ papillomas than in Itga11−/− papillomas." (PMID 36003785, 2022).
parasitic diseases (1 paper, 2022). "COL1A1, COL1A2, and COL3A1 have been previously reported to be abnormally overexpressed in some tumors and parasitic diseases." (PMID 36034715, 2022).
Parkinson disease (1 paper, 2013). A progressive degenerative disorder of the central nervous system characterized by loss of dopamine producing neurons in the substantia nigra and the presence of Lewy bodies in the substantia nigra and locus coeruleus. "The other markers (i.e., CAPN6, COL1A2, COL3A1, GALA1 and MTNR1B) belong to gene families with a known role in other neurodegenerative diseases, such as Alzheimer’s or Parkinson’s disease in humans." (PMID 23497022, 2013).
pheochromocytoma (1 paper, 2021). "In conclusion, we found that the inactivation of pVHL in pheochromocytoma led to the up-regulation of the seven novel genes, such as CTGF, SDCBP, CYR61, COL3A1, COL1A1, COL5A2, and SERPINE1." (PMID 33828526, 2021).
platelet disorders (1 paper, 2025). "As such, COL3A1 could be added to gene panels incorporating genetic causes of bleeding and platelet disorders." (PMID 39730916, 2025).
pneumonitis (1 paper, 2018). An inflammatory process affecting the lung parenchyma. "The lung of BLM group developed pneumonitis with severe cellular infiltrations at 7 days and significant collagen deposition (MT) and higher expression of Col1a1, and Col3a1 at 21 days post-administration." (PMID 29497425, 2018).
polymicrogyria (1 paper, 2024). A developmental brain abnormality characterized by an excessive amount of small convolutions on the surface of the brain and cognitive dysfunction. "The biallelic mutation of Col3a1 can lead to a special brain phenotype, including bilateral frontoparietal polymicrogyria with cobblestone variants, cerebellar microcysts, and white matter abnormalities." (PMID 39295096, 2024).
Pruritus (1 paper, 2023). Pruritus is an itch or a sensation that makes a person want to scratch. "The AA genotype of COL3A1/rs1800255 appears to be associated with the mild course of AD, and mild pruritus occurrence with the GG genotype appears to be associated with the severe AD course." (PMID 37109047, 2023). "Furthermore, the AA genotype of /COL3A1/rs1800255 was dominant in the group of patients with mild pruritus and was significantly associated with the occurrence of mild pruritus (OR = 18.5; 95% Cl: 3.48–98.40; p = 0.0006)." (PMID 37109047, 2023). "In addition, according to the average pruritus level, the patients with the AA genotype of Col3A1/rs1800255 significantly differed from patients with AG and GG genotypes (2.5 vs. 5.8 p = 0.009; 2.5 vs. 6.8 p = 0.006, respectively)." (PMID 37109047, 2023).
Pulmonary hemorrhage (1 paper, 2025). Pulmonary hemorrhage is a bleeding within the lungs. "Two novel and two pathogenic mutations in COL3A1 gene associated with vEDS, COL1A1, COL1A2, TNXB gene mutations of non-vascular types underlying EDS and COL4A2 gene associated with collagen synthesis were found in patients presenting with pulmonary hemorrhage." (PMID 40598578, 2025).
pulmonary hypertension (1 paper, 2022). Increased pressure within the pulmonary circulation due to lung or heart disorder. "CIRP-/- mice showed attenuated induction of α-SMA and collagens (Col1a1, Col3a1), reduced hydroxyproline content, decreased histological fibrosis scores, and improved pulmonary hypertension as compared to WT mice." (PMID 35377906, 2022).
pulmonary neuroendocrine neoplasms (1 paper, 2023). "In a recent study, the up-regulation of six fibrogenic genes (COL5A2, COL1A2, COL3A1, ITGA5, ITGB1, and ITGB1) in pulmonary neuroendocrine carcinoma and the down-regulation of pulmonary neuroendocrine neoplasms were strongly related to no metastasis and overall survival." (PMID 37047300, 2023).
rectal adenocarcinoma (1 paper, 2023). "tool to screen for GUCA2A and COL3A1 expression in multiple cancer types and found that GUCA2A was significantly downregulated in 11 cancer type and COL3A1 was significantly upregulated in 18 cancer type, especially in colon and rectal adenocarcinoma." (PMID 37816854, 2023).
rotator cuff tear (1 paper, 2015). "Although previous studies demonstrated the involvement of COL3A1 in rotator cuff tear, we believe that further investigations are still necessary to understand the role of this gene in rotator cuff diseases." (PMID 25768100, 2015).
skin changes (1 paper, 2024). "The gene sets encompass numerous genes previously implicated in the pathogenesis of SSc, such as Acta2, Col1a1, Col3a1, Smad3, Ctgf, Msr1, Cd4, Cd8a and Cd68, supporting the potential of anti-PRMT5 in induction of SSc-like skin changes." (PMID 38684324, 2024).
Skin ulcer (1 paper, 2024). A discontinuity of the skin exhibiting complete loss of the epidermis and often portions of the dermis and even subcutaneous fat. "A novel recombinant extra domain-B fibronectin (EDB-FN)-COL3A1 fusion protein (rhFEB) was designed to mimic the ECM to promote chronic and refractory skin ulcer wound healing." (PMID 38285241, 2024).
small cell lung carcinoma (1 paper, 2020). Small cell lung cancer (SCLC) is a highly aggressive malignant neoplasm, accounting for 10-15% of lung cancer cases, characterized byrapid growth, and early metastasis. "And co‐analysed COL3A1 and 184 KEGG pathways, heatmap plot showed the top four KEGG pathways were ECM receptor interaction (R = 0.21, P < 0.001), N‐glycan biosynthesis (R = 0.19, P < 0.001), small cell lung cancer (R = 0.18, P < 0.001) and glycosaminoglycan degradation (R = 0.18, P < 0.001)." (PMID 32757451, 2020).
soft tissue sarcoma (1 paper, 2023). A malignant neoplasm arising from muscle tissue, adipose tissue, blood vessels, fibrous tissue, or other supportive tissues excluding the bones. "A newly developed canine soft tissue sarcoma cell line, FACC-19CSTS36, with a Sanger sequence confirmed COL3A1-PDGFB fusion was tested for sensitivity to imatinib, a tyrosine kinase inhibitor capable of inhibiting v-Abl, c-Kit, and PDGFR." (PMID 37369741, 2023).
Spina bifida occulta (1 paper, 2022). The closed form of spina bifida with incomplete closure of a vertebral body with intact overlying skin. "In addition, known pathogenic missense mutation c.1744G > A(p.Gly582Ser) in COL3A1, which has been reported to cause Ehlers-Danlos syndrome IV16, was found in P175 with spina bifida occulta at the sacral vertebrae." (PMID 35562572, 2022).
stomach adenocarcinoma (1 paper, 2022). "After that, we investigated whether the high expression of dual combinations of COL1A1, COL1A2, COL3A1, or COL5A1 exacerbates the outcome of CAF infiltration in stomach adenocarcinoma." (PMID 35739492, 2022).
systemic lupus erythematosus (1 paper, 2020). An autoimmune multi-organ disease typically associated with vasculopathy and autoantibody production. "Co‐expressed circle plot of COL3A1, propanoate metabolism, systemic lupus erythematosus and proteasome illustrated the interplay relationship." (PMID 32757451, 2020). "Additionally, according to co‐analysis with COL3A1 in heatmap, propanoate metabolism was selected form propanoate metabolism (R = −0.140, P < 0.001), systemic lupus erythematosus (R = 0.130, P < 0.001) and proteasome (R = 0.100, P < 0.001)." (PMID 32757451, 2020). "Besides, for the relationship with COL3A1, propanoate metabolism (P < 0.001), systemic lupus erythematosus (P = 0.003) and proteasome (P = 0.027) were all significant." (PMID 32757451, 2020).
uremia (1 paper, 2016). A clinical syndrome associated with the retention of renal waste products or uremic toxins in the blood. "Moreover, induction of uremia increased expression of fibrosis-related genes, most importantly Col1a1, Col3a1, and Fn1." (PMID 27992511, 2016).
urothelial carcinoma (1 paper, 2022). A malignant neoplasm derived from the transitional epithelium of the urinary tract (urinary bladder, ureter, urethra, or renal pelvis). "In contrast to this, COL3A1 was found to be under-expressed in urine samples as well, despite the fact that the majority of these patients had high-grade urothelial carcinomas." (PMID 35884419, 2022).
Uterine leiomyoma (1 paper, 2022). The presence of a leiomyoma of the uterus. "Chuang’s research manifested that the expression of miR-29c in uterine leiomyoma was inhibited, and its expression was negatively correlated with the expression of COL3A1 and DNMT3A." (PMID 35113040, 2022).
tumor (179 papers, 2010 to 2026). "Within this aggressive subpopulation, Collagen type III alpha 1 (COL3A1) emerged as a tumor-intrinsic gene associated with extracellular matrix remodeling and angiogenic signaling." (PMID 42193303, 2026). "Several genes, including S100A4, ITGAV, and COL3A1, previously linked to tumor progression and poor prognosis, emerged in our study as robust prognostic indicators." (PMID 40943183, 2025). "Tumor-associated fibroblasts have been implicated in the cancer microenvironment, with certain molecules (such as COL3A1) produced by these cells being associated with tumorigenesis and metastasis." (PMID 39761856, 2025). "CD8+ T cells, activated CD4+ memory T cells, and resting NK cells infiltrated tumours of patients with COL3A1 mutations." (PMID 39530091, 2024). "In this study, ECM stiffness is favored by the overexpression of collagen type III alpha 1 chain (COL3A1) as a component of tumor-associated aligned collagen that promotes iCCA cell migration." (PMID 39199659, 2024). "Among the collagens regulated by Sin3B loss, Col3a1 stood out as highly expressed in PDAC tumor cells, thus warranting for further validation." (PMID 39316363, 2024). "Genes such as COL1A1, COL1A2, and COL3A1, which are implicated in the tumor microenvironment, and immune-related genes, such as THY1, IRF5, and HLA-DRA, exhibited significant expression level changes." (PMID 38672562, 2024). "Some studies have also reported that HMOX1, SST, PLA2G2A, KRT4 and COL3A1 are associated with tumor progression and prognosis." (PMID 38461430, 2024). "This phenomenon reminded us that the risk model and COL3A1 alone have fallen short of presenting the real stromal status in the tumor microenvironment." (PMID 36039012, 2023). "In particular, we focused on the effects of the overexpression of collagen type III alpha 1 chain (COL3A1) in iCCA, thus providing evidences that COL3A1 promotes iCCA cells migration and is a component of tumor-associated aligned collagen." (PMID 31687002, 2019). "Virtual knockout further suggested that COL3A1 may be associated with transcriptional programs involved in PD-L1 upstream signaling pathways, indicating a potential indirect link between tumor-intrinsic states and immune regulatory networks." (PMID 42193303, 2026). "The COL3A1-mutated tumours exhibited an elevated ORR and disease control rates." (PMID 39530091, 2024). "Interestingly, some of the genes involved in collagen organization, including DCN, which has been associated with tumor suppressive activities, or COL3A1 were downregulated upon co-culture with organoids in both NFs and CAFs." (PMID 36868311, 2023). "In addition, it was reported that COL3A1 up-regulation cause extracellular matrix changes and reduced tumor perfusion, while the hypoxic micro-environment caused by hypoperfusion was considered to be the main reason for forcing cancer cells to metastasize." (PMID 32766145, 2020). "Therefore, the reduction of tumor perfusion caused by up-regulation of COL3A1 was likely to be one of the reasons for the increased ability of TNBC cells to metastasis." (PMID 32766145, 2020). "Functional and pathway enrichment analysis demonstrated that COL3A1 is overrepresented in pathway of focal adhesion, which associated with tumor progression and might cause metastasis." (PMID 29050298, 2017). "Collagen proteins (COL1A1, COL1A2, COL3A1, COL11A1) were associated with tumor progression and metastasis." (PMID 40867231, 2025). "Overexpression of COL3A1 contributes to increased ECM stiffness, which in turn enhances tumor cell migration and invasion, a hallmark of early cancer progression." (PMID 41465316, 2025). "They identified, among others, Dcn, Sparc, Col1a2, and Col3a1 as significantly upregulated in CTCs compared to the primary tumor." (PMID 40227761, 2025). "Recent spatial proteomics analysis showed that COL1A2 and COL3A1 were more abundant in the region where the brain and tumour interface." (PMID 39350478, 2024).